BCL2 (BCL2 apoptosis regulator)
Diseases named in the same sentence as BCL2 in open-access papers (continued):
Sharing a sentence is not in itself a finding about the gene and the disease.
cancer (continued). "BAX belongs to the Bcl-2 gene family of proapoptotic proteins and frameshift mutations correlate to cancer development in different type of organs." (PMID 33572923, 2021). "We here demonstrated both NMR-based structural approaches and anti-cancer drug discovery approaches to functional refolded Bcl-2 protein and its truncated variants in membrane-mimicking micellar environment." (PMID 33800399, 2021). "The ability of these molecules to inhibit the antiapoptotic Bcl-2 protein was associated with the sensitization of cancer cells to apoptosis." (PMID 35003514, 2021). "Meanwhile, HT-29 cancer cells underwent apoptosis by increased Bax expression and loss of Bcl-2 after treatment with AgCTP NPs (25 ng/mL)." (PMID 34567145, 2021). "One of the most commonly known apoptotic factors linked to cancer cell resistance to paclitaxel is Bcl-2 protein, a proton-efflux pump acting as a pro-survival factor." (PMID 33802861, 2021). "The Bcl-2 gene family, which is normally involved in anti-apoptotic activities, can potentially cause cancer, and cancer-related proteins such as Myb and Ras induce high levels of Bcl-2 in hematopoietic cells." (PMID 33833342, 2021). "Our data clearly suggest that high concentrations of the DK-compounds induce apoptosis in HER2-positive cancer cells, which is associated with the deregulation of Bcl-2/Bax/caspase-3." (PMID 34502529, 2021). "It is noteworthy that the significant decrease in the RAR protein level was associated with the up‐regulation of Bcl‐2 protein in the cancer tissues of patients." (PMID 33090723, 2020). "Most cancer cells evade apoptosis through caspase inhibition, upregulation of Bcl-2 (in more than 50% of all types of cancers), and loss of BAX/BAK and become resistant to anticancer drugs." (PMID 33027952, 2020). "Upregulated Bax and caspase-3 expression, alongside Bcl-2 downregulation, which are associated with cancer cell apoptosis, have also been observed following administration of a modified Si-Jun-Zi decoction." (PMID 32595757, 2020). "This rendered the drug inefficient in disrupting Bcl-2’s association with pro-apoptotic family members and enabled cancer cell resistance towards venetoclax." (PMID 32708132, 2020). "ECPU-0001, an efficient tumoricidal agent, exhibited impressive anti-cancer activity and translated to the treatment of lung adenosarcoma by targeting the Bcl-2-associated intrinsic pathway of apoptosis." (PMID 33114695, 2020). "The BCL2 protein regulates apoptosis and was the first apoptosis modulator described to be associated with cancer." (PMID 33067577, 2020). "In our study, both genetic and drug-induced BMI1 regulation decreased RNA expression of BCL-2, a known protein with anti-apoptotic functions, suggesting deregulation of both mitosis and cancer-associated survival mechanisms upon BMI1 inhibition." (PMID 32343689, 2020). "C5-inducing apoptosis was inhibited by Flag-Bcl-2 overexpression in A549 cells, and such findings indicate that Bcl-2 is likely to be susceptible to C5-induced apoptosis in cancer cells." (PMID 32075108, 2020). "As an anti-apoptotic protein, although the promotion of Bcl-2 has led us to consider an increase in the risk of cancer, its overexpression has been proven to resist Aβ-induced PC12 cell death." (PMID 33328962, 2020). "Dual down-regulation of both major anti-apoptotic proteins, XIAP and Bcl-2, has been reported to cause enhanced apoptosis, increased sensitivity to chemotherapy and can overcome resistance of cancer cells." (PMID 32587235, 2020). "BCL2 is a key regulator of apoptosis whose dysregulation can cause various pathological consequences including the development of cancer." (PMID 32883271, 2020).
cancer (continued). "Many human cancers over-express B cell lymphoma 2 (Bcl-2) or X-linked inhibitor of apoptosis (IAP) proteins to evade cell death." (PMID 32587235, 2020). "While it remains to be elucidated how miR-7-3p enhances the sensitivity of cancer cells to luteolin and silibinin, miR-7-3p is recognized to effectively reduce the level of anti-apoptotic factors, such as BCL-2 and X-linked inhibitor of apoptosis (XIAP)." (PMID 33066509, 2020). "This can be linked to the work of Wang and co-workers, who have linked the aberrant expression of Bcl-2 protein with death resistance of cancer as a result of increased production of hydrogen peroxide." (PMID 33203053, 2020). "We found that curcumin and cisplatin treatment in PTC cells inhibited Bcl2 expression and elevated Bax expression (in other words, increasing the Bax/Bcl2 ratio), which supports earlier findings underlying apoptosis in cancer cells." (PMID 31936675, 2020). "B-cell lymphoma-2 (Bcl-2)-mediated suppression of apoptosis is an important molecular hallmark of cancer." (PMID 33149126, 2020). "Overexpression of Bcl-2 typically results in cancer cell resistance to cancer factors, which is associated with abnormal changes in PI3K/AKT pathways." (PMID 32973135, 2020). "Among the mechanisms implicated in cancer drug resistance, there are abnormalities in the genes and proteins of the B-cell lymphoma 2 (Bcl-2) family that control the apoptosis mitochondrial pathway." (PMID 33312200, 2020). "Bax/Bcl2 expression ratio is important at clinical level as a remarkable prognostic and diagnostic marker in different diseases including cancers." (PMID 32005894, 2020). "To verify the revealed inverse association between protein expression of Cx43 and Bcl-2 we used the mRNA expression data of head and neck tumors from TCGA (The Cancer Genome Atlas Program)." (PMID 31766723, 2019). "It is thus evident that the downregulation of this family of expressions is closely associated with the upregulation of BCL2 proteins, which plays a critical role in regulating major types of cell death, contributing to cancer development and progression." (PMID 30621620, 2019). "Overexpression or loss of pro- and anti-apoptotic BCL-2 proteins, respectively, is typical in a wide range of human cancer and has frequently been linked with increased chemoresistance and radioresistance." (PMID 30621025, 2019). "The pro-apoptotic protein (Bax and Caspase3) and the anti-apoptotic protein (Bcl2) are the kinds of the proteins related to cell apoptosis pathway and implicated in cancer radiotherapy." (PMID 31870109, 2019). "Cancer cells evade apoptotic mechanisms through different mechanisms: the most frequent mechanism is represented by overexpression of anti-apoptotic BCL-2 proteins and loss of BAX or BAK; inhibition of caspase function." (PMID 30813354, 2019). "Amplification and translocation of BCL2 genes are shown to be equally common mechanisms that cause its overexpression in human cancer cells." (PMID 30682877, 2019). "The depletion of mitochondrial DNA (mtDNA) has been reported in numerous cancers in vivo and has been implicated in increasing the expression of anti-apoptotic genes, such as Bcl2." (PMID 31261935, 2019). "DTX induces apoptosis in cancer cells, as demonstrated by associated changes in the mitochondrial membrane potential and overexpression of BCL2." (PMID 31540423, 2019).
cancer (continued). "IMP, a furanocoumarin found widely in umbelliferous plants was reported to show anti-cancer activity by the upregulation of Bax expression and the downregulation of Bcl-2 expression which caused apoptosis." (PMID 31673107, 2019). "In the work presented here, we used pan-cancer genomic data from hundreds of patients to show that a single-nucleotide variant in the BCL2 sequence can predict a patient’s response to paclitaxel, a widely used chemotherapy." (PMID 31044156, 2019). "Since paclitaxel is known to target BCL2 and TUBB1, we used pan-cancer genomic data from hundreds of patients to show that a single-nucleotide variant in the BCL2 sequence can predict a patient’s response to paclitaxel." (PMID 31044156, 2019). "For example, Hedgehog signaling, which is aberrantly activated in several types of cancers, linked Wnt signaling pathways with cell survival genes BCL2 and EMT driver genes SNAI1/2, ZEB1/2 through epigenetic or genetic alterations during carcinogenesis." (PMID 30548372, 2019). "The combination of MCL1 inhibitors with the BCL-2 specific inhibitor venetoclax should be effective against LKB1-mutated cancers and should induce a pronounced sensitization to standard chemotherapy." (PMID 31781355, 2019). "Bcl-2 protein is a product of Bcl-2 pro-oncogene encoding, which promotes the survival of cancer cells and inhibits apoptosis." (PMID 31839821, 2019). "Reliance on anti-apoptotic BCL2 proteins is a hallmark of many cancers, making them ideal targets for drug therapy." (PMID 30796196, 2019). "Antiapoptotic BCL‐2 proteins are frequently overexpressed in cancer and are associated with an aggressive, treatment‐refractory disease." (PMID 31228231, 2019). "Cancers often overexpress anti-apoptotic Bcl-2 proteins for cell death evasion, a recognized hallmark of cancer progression." (PMID 31595181, 2019). "The main finding of this study is that constitutive IP3 signaling, besides high IP3R2-expression levels, is an important determinant that underlies cancer cells’ addiction to Bcl-2 at the ER Ca2+ stores." (PMID 29899382, 2019). "As an anti-apoptotic pro-survival protein, Bcl-2 overexpression in human and feline cancers would be expected to be associated with a more aggressive behavior." (PMID 30630524, 2019). "BCL2 underexpression has been linked to more aggressive ECs, including high-grade cancers, advanced stage cancers, and cancers displaying lymph node invasion." (PMID 29653556, 2018). "They suggest BCL2 inhibition alone or in combination with EZH2 inhibition represents urgently needed therapeutic strategy for ARID1A-mutated cancers." (PMID 30297712, 2018). "While Bcl-2 is classified as an oncogene because it causes the onset of many cancers including lymphoma, it also sustains the function of thymocyte subpopulations during development." (PMID 29323189, 2018). "In K562/A02, a multidrug-resistant variant of CML K562 cells with GCS and Bcl-2 co-overexpression, apoptosis was enhanced by adriamycin (a chemotherapeutic agent used for treatment of various cancers) through downregulation of Bcl-2 via the ERK pathway." (PMID 29773994, 2018). "Studies have shown that the Bax/Bcl-2 ratio is an important index which determines the susceptibility to apoptosis in cancer cells." (PMID 29338036, 2018). "The Bcl-2/Bax protein in the mitochondria dictates the susceptibility of cancer cells to undergo apoptosis." (PMID 30410940, 2018). "NF-κB has been shown to regulate the transcription of genes encoding Bcl-2 and Bcl-xL in other cell types such as cancer cells and CD4+ T lymphocytes." (PMID 29848490, 2018).
cancer (continued). "Mcl-1 is a key member of the Bcl-2 anti-apoptotic family, is commonly overexpressed in a number of cancers, and is a major cause of resistance to radio- and chemotherapies." (PMID 29649138, 2018). "We further determined that the paclitaxel resistant cancer cells with elevated Bcl-2 were more susceptible to a Nur77 peptide capable of converting Bcl-2 from an anti-apoptotic protein to a pro-apoptotic protein." (PMID 29899843, 2018). "KSHV encodes a viral homolog of Bcl-2 named as KS-Bcl-2, which inhibits apoptosis and autophagy when over expressed in cancer cells have recently been found to be essential for virus replication." (PMID 28400769, 2017). "Recently,polymorphism in Bcl-2 gene, variant in promoter region rs2279115 and rs1801018, have been reported to be associated with cancer susceptibility and prognosis many times." (PMID 28445963, 2017). "Many studies have shown that Stat3 plays oncogenic roles by promoting the expression of cancer-associated genes such as cyclinD1, c-Myc, Cox-2, and Bcl-2." (PMID 29245928, 2017). "For example, in GEAR, BCL2 was recorded to be associated with resistance to Cisplatin, a drug widely used for cancer, where the cancer cells with expression of BCL2 were reported to be more significantly resistant to Cisplatin24." (PMID 28294141, 2017). "Diallyl trisulfide inhibits the growth of human cancer cells by inducing apoptosis in association with downregulation of Bcl-2 expression, induction of caspases and regulation of PI3 K/Akt and JNK pathways." (PMID 28852876, 2017). "For example, Bcl-2 and Mcl-1 are highly expressed in cancers, promote cancer cell survival and are associated with poor therapeutic outcomes." (PMID 29156771, 2017). "The constitutive activation of STAT3 has been implicated in the regulation of cancer cell survival (survivin, Bcl-xL), proliferation (cyclin D1/D2) and anti-apoptosis (Bcl-2)." (PMID 28114390, 2017). "Dysregulated expression and function of Bcl-2 proteins have been not only implicated in oncogenesis but also represent an “Achilles’ heel” in cancer cells that can be exploited by the use of Bcl-2 inhibitors." (PMID 28516063, 2017). "Currently research shows that cancer, neurodegenerative disorders, ischemia and autoimmune diseases are associated with Bcl-2 function abnormalities." (PMID 28445963, 2017). "A functional single-nucleotide polymorphism (c.-938C>A, rs2279115) in the inhibitory P2 BCL2 gene promoter has been associated with clinical outcomes in various types of cancer." (PMID 28396899, 2017). "BCL-2 overexpression occurs in many cancer types and is associated with chemo-resistance and radio-resistance." (PMID 27875990, 2016). "The overexpression of the Bcl-2 protein is associated with malignancy and with poor prognosis in various cancers." (PMID 26927133, 2016). "Activation of pro-survival B cell lymphoma 2 (BCL2) family genes (e.g. MCL1, BCL2 and BCLX) is common hallmark of cancer and contributes to tumorigenesis via BCL2-mediated apoptosis." (PMID 27722045, 2016). "Attenuated STAT3 signaling pathway results in reduced levels of cyclinD1 and Bcl-2, which caused cancer cells being arrested in G1/S phases and ultimately apoptotic cell death." (PMID 27058422, 2016). "Several studies have shown that the modulation of BCL2 expression affects cell susceptibility to apoptosis induced by anti-cancer drugs." (PMID 27386062, 2016). "The anti-apoptotic protein Bcl-2 has been proven to cause resistance to cancer treatment by forming heterodimers with a number of pro-apoptotic proteins." (PMID 26846780, 2016). "Altogether, our data support a novel model, whereby cancer-associated La protein contributes to cisplatin resistance by stimulating the translation of anti-apoptotic factor Bcl2 in HNSCC cells." (PMID 27105491, 2016).
cancer (continued). "Anti-apoptotic Bcl-2 proteins are frequently overexpressed in human cancers and associated with chemotherapeutic resistance and relapse." (PMID 26758417, 2016). "The BCL-2 rs2279115 polymorphism has been extensively studied in multiple cancer types, including ESCC." (PMID 26132559, 2015). "The promotion of apoptosis by As2O3 was further explored by examining the expression level of the anti-apoptotic protein Bcl-2, which has been implicated in several types of cancer." (PMID 26622477, 2015). "We recently reported a novel interaction between Bcl-2 and Rac1 and linked that to the ability of Bcl-2 to induce a pro-oxidant state in cancer cells." (PMID 26430964, 2015). "The CdCl2(C14H21N3O2) complex treatment group caused down-regulation of anti-apoptotic protein Bcl-2 by inducing anti-proliferative effects in the cancer control groups (47% and 43% respectively in groups treated with 25 mg/kg and 50 mg/kg of complex)." (PMID 26201720, 2015). "Further studies will be needed to test the underlying mechanisms of VS-5584 resistance by Bcl-xL/Bcl-2, and to repeat these results in other cancer cells." (PMID 26204252, 2015). "Bcl-2 elevation contributes to apoptosis resistance in malignant cells, a hallmark of cancer that represents a major hurdle in cancer treatment." (PMID 26317541, 2015). "So impairment of Bcl-2 gene expression is a hallmark of cancer and can result in resistance to chemotherapy." (PMID 26535028, 2015). "Bcl2 is a known anti-apoptotic protein that is frequently examined for potential clinical use as a prognostic biomarker in cancer, and its overexpression is associated with resistance to cytotoxic drugs such as cisplatin and 5-fluorouracil." (PMID 26074733, 2015). "With Bcl-2, we studied an anti-apoptotic cytosolic protein that can decrease the susceptibility of cancer cells to induction of apoptosis by granzyme B." (PMID 26510188, 2015). "Bcl-2 and Akt as well as NF-κB are found to be highly expressed in some type of cancers, which are associated with drug resistance." (PMID 26421052, 2015). "In a further study of the possible mechanism underlying plasma-induced cancer cell apoptosis at 24 h, we determined the mRNA gene expressions of Bcl-2, BAX, BAK1 and H2AX by real time quantitative PCR analysis." (PMID 25715710, 2015). "G-quadruplexes have been shown to be present in regions of biological significance, such as human telomeres and in the promoter regions of several cancer-linked genes, including c-myc, bcl-2, c-kit, VEGF, Ras, HIF-1α, and Rb41,42." (PMID 25449683, 2015). "Damage to the BCL-2 gene has been identified as a cause of many cancers, including melanoma, breast cancer and prostate cancer." (PMID 25901161, 2015). "Increased Bcl-2 expression is linked to chemoresistance and targeting this has been an emerging strategy in cancer treatment." (PMID 26416353, 2015). "High expression levels of the BCL2 gene have been associated with drug resistance of the cancer cells Additionally, alongside being chemoresistant, these BCCs have been recognized to express genes linked to pluripotency." (PMID 25837691, 2015). "Bcl-2 gene damage is a major cause of cancer and resistance to cancer treatments because over-expression of anti-apoptotic genes and under-expression of pro-apoptotic genes results in lack of cell death." (PMID 25071577, 2014). "This meta-analysis was performed to evaluate the relationships of Bcl-2 -938 C>A polymorphism (rs2279115) with susceptibility and prognosis of cancer." (PMID 25430556, 2014). "It appears that the ratio of pro- versus anti-apoptotic Bcl-2 proteins is crucial in regulating the susceptibility of cancer cells to apoptosis." (PMID 24765133, 2014).